CDH1 (cadherin 1)
Diseases named in the same sentence as CDH1 in open-access papers (continued):
Sharing a sentence is not in itself a finding about the gene and the disease.
lymph node metastasis (152 papers, 1996 to 2026). "The multivariable analysis suggested that the risk of lymph node metastasis is 2.5 times in CDH1 heterogeneous methylation group (OR = 2.512, 95% CI 1.135, 5.557, P = 0.023)." (PMID 34539742, 2021). "The multivariable analysis suggested that CDH1 methylation heterogeneity is associated with lymph node metastasis and HIN1 methylation heterogeneity is associated with extra-thyroidal extension." (PMID 34539742, 2021). "Univariate logistic analysis indicated that CDH1 methylation heterogeneity, age and tumor size are associated with lymph node metastasis, independently (P = 0.026, P = 0.000, P = 0.040)." (PMID 34539742, 2021). "Interesting, the multivariable analysis suggested that the risk of lymph node metastasis is 2.5 times in CDH1 heterogeneous methylation group compare to CDH1 homogeneous methylation group (OR = 2.512, 95% CI 1.135, 5.557, P = 0.023)." (PMID 34539742, 2021). "It is worth noting that abnormal cytoplasmic CDH1 in PC tissues, and higher cytoplasmic CDH1 expression were associated with more aggressive tumor-associated variables, including lymph node metastasis and advanced clinical stage." (PMID 26918727, 2016). "A multivariate logistic regression revealed that lower CDH-1 mRNA expression was the independent risk factor affecting lymph node metastasis (p = 0.041)." (PMID 24887090, 2014). "Interestingly, we identified that lymph node metastasis only and CDH1 wild type were associated with higher ORR and longer PFS in gastric SRCC treated with PD-1 antibody." (PMID 36675776, 2023). "Moreover, it showed the lowering CDH-1 mRNA expression may increase risk in affecting lymph node metastasis." (PMID 28740192, 2017). "Univariate analysis showed that dMMR, lymph node metastasis only, PD-L1 CPS CPS ≥ 5, and CDH1 wild type were significantly associated with longer PFS." (PMID 36675776, 2023). "Multivariate analysis showed that dMMR, PD-L1 CPS CPS ≥ 5, CDH1 wild type, and lymph node metastasis only were independent prognostic factors for PFS." (PMID 36675776, 2023). "CDH1 is frequently lost in PDAC cells, which associates with worse clinical features including lymph node metastases, and a poor prognosis." (PMID 36359732, 2022). "Most importantly, patients with high co-expression of nuclear HDAC3 and cytoplasmic CDH1 had shorter survival times (P < 0.001), more frequent lymph node metastasis (P < 0.001), and advanced clinical stage (P < 0.001)." (PMID 26918727, 2016). "High cytoplasmic CDH1 strongly correlated with lymph node metastasis (N classification, P < 0.001) and advanced clinical stage (P < 0.001)." (PMID 26918727, 2016). "In contrast, reduced membrane CDH1 correlated with lymph node metastasis, advanced clinical stage, and shorter survival time." (PMID 26918727, 2016). "Our results show that increases in both membrane and cytoplasmic CDH1 correlate with lymph node metastasis (P = 0.026 and P < 0.001, respectively) and clinical stage (P = 0.020 and P < 0.001, respectively)." (PMID 26918727, 2016). "CDH1 cell membrane expression correlated with lymph node metastasis (P = 0.026) and clinical stage (P = 0.020)." (PMID 26918727, 2016). "Nevertheless, reduced immunohistochemical expression of CDH-1 in the mammary gland was related to malignancy, invasive growth, lymph node metastasis, necrosis, differentiation grade, size and ulceration of the tumor in dogs." (PMID 26370564, 2015). "A univariate analysis showed that higher Cox-2 mRNA expression (p = 0.037), lower CDH-1 mRNA expression (p = 0.020), and advanced T-classification (p = 0.036) were significantly correlated with lymph node metastasis in TSCC." (PMID 24887090, 2014). "Higher Cox-2 mRNA expression was significantly correlated with lymph node metastasis (p = 0.037), while lower CDH-1 expression was correlated with both advanced T-classification (p = 0.041) and lymph node metastasis (p = 0.020)." (PMID 24887090, 2014).
lymph node metastasis (continued). "For lymph node metastasis, ten CpGs from six genes were found to be significant: CDH1 (site 10), CDH13 (sites 7 and 8), MINT3 (sites 3 and 4), CXCL12 (sites 1 and 3), RARB (site 6) and APC (sites 1 and 6)." (PMID 25052224, 2014). "GC patients with N0 lymph node metastasis also presented a marked lower rate of CDH1 methylation, demonstrated its correlation to the development of GC." (PMID 22514028, 2012). "We also found a significant association between patients with lymph node metastasis and overexpression of BMP7 (47.4%, P=0.005), CALD1 (42.1%, P=0.020), CDH1 (52.6%, P=0.001), COL3A1 (42.1%, P=0.020), EGFR (47.4%, P=0.005), ERBB3 (57.9%, P=0.000), PLEK2 (47.4%, P=0.024), and TCF4 (52.6%, P=0.001)." (PMID 34527572, 2021). "Similarly, in dogs, reduced immunostaining for CDH-1 is correlated with increased invasion potential, lymph node metastasis, histological grade and infiltration." (PMID 26370564, 2015). "Lower CDH-1 mRNA expression alone, and not Cox-2 mRNA expression or T-classification, was found to be the independent risk factor affecting lymph node metastasis in this series (odds ratio = 0.905, p = 0.041)." (PMID 24887090, 2014). "The progression-free survival was significantly longer in patients with dMMR, lymph node metastasis only, PD-L1 combined positive score (CPS) ≥ 5, and CDH1 wild type." (PMID 36675776, 2023). "In this study, we found that the decreased expression of CDH1 or CTNNB1 in the cell membrane in cancer tissues accompanied the local progression and lymph node metastasis of esophageal cancer." (PMID 27600761, 2016). "In CDH1, the patients harboring AA or GA genotype of rs7186053 (G>A) had favorable event-free survival in less aggressive tumor subgroups, such as in ER-positive group, PR-positive group and negative lymph node metastasis group." (PMID 26285011, 2015). "Moreover, the rate of CDH1 methylation was 95.7% (44/46) in GC tissues with lymph node metastasis, while was 67.4% (31/46) in GC tissues without lymph node metastasis, also with a significant difference between these two groups (χ2 = 12.195, P < 0.001)." (PMID 22514028, 2012). "CDH13 and RIL (PDLIM4) expression levels were significantly decreased in lymph node metastasis, whereas no significantly changes in the expression of RASSF1A, RARβ2 and CDH1 mRNAs were observed." (PMID 20642860, 2010). "Also, CDH2 positivity in IHC staining was correlated to lymph node metastasis of TNBC, but CDH1 was not." (PMID 28392805, 2017).
breast tumor (146 papers, 2006 to 2026). "For example, the proto-oncogene ROS1 encodes a receptor tyrosine kinase (ROS1), and a preclinical study of CDH1 synthetic lethality interactions has identified ROS1 as a potential target in breast tumor cells with CRISPR/Cas9-engineered CDH1 mutations." (PMID 39941785, 2025). "In breast tumor cells, it was found that CDH1 promoter hypermethylation caused the reduced expression of E-cadherin rather than its mutational inactivation." (PMID 36768182, 2023). "Loss of E-cadherin expression in breast tumors has been associated with genetic and epigenetic alterations, including truncating pathogenic variants in the CDH1 coding sequence, loss of heterozygosity, and methylation of the CDH1 promoter." (PMID 36553480, 2022). "A mutation at the same site (D254Y) has been recorded in COSMIC in a breast tumour and 211 somatic mutations have been observed in the 2732 samples sequenced for CDH1 in COSMIC." (PMID 21781349, 2011). "Future investigations will therefore be directed at verification of this transcriptional programme associated with CDH1 methylation in primary breast tumour samples and an association with disease outcome." (PMID 16495925, 2006). "To identify differentially expressed genes associated with differences in E-cadherin expression, we first compared the seven breast tumour cell lines in the ‘Epithelial’ cluster with CDH1 mutations with 12 harbouring wild-type CDH1 from the same cluster." (PMID 16495925, 2006). "Moreover, the normalized expression of CDH1 is significantly reduced in tumours that arise in carriers of BRCA1 mutations relative to sporadic breast tumors." (PMID 28427147, 2017). "RNAseq data of the breast tumor revealed the presence of one novel transcript CDH1 r.1831_1936del due to the use of the cryptic exonic splicing donor site at the DNA codon position CDH1 c.1830 on exon 12, causing the loss of the last 160 nucleotides of exon 12 (CDH1 Δ12q)." (PMID 41154377, 2025). "Due to its high penetrance, any person carrying the CDH1 gene should be managed by a prophylactic gastrectomy and D1 lymphadenectomy with close follow up for any future breast neoplasm." (PMID 38394940, 2024). "The cell adhesion glycoprotein E-cadherin (CDH1) is commonly inactivated and reduced in progressive breast tumors." (PMID 34277614, 2021). "Our data suggest that CDH1 genetic testing should be considered also in other cancers, especially breast tumors." (PMID 34066044, 2021). "Although mechanisms of CDH1 inactivation are still complex to manage routinely, it is reasonable to evaluate E‐cad expression in breast tumours using standard methods, such as immunohistochemistry." (PMID 32301282, 2020). "Later on, the impact of hypermethylation on 6 tumour suppressor genes in tumour progression was evaluated using a series of 151 primary breast tumours, in which the CDH1 promoter was found to be hypermethylated in 53% of cases." (PMID 32301282, 2020). "The progression of breast tumor cells is associated with EMT and CDH1 is one of the fundamental genes in inhibition of metastasis." (PMID 32257110, 2020). "The only tumour suppressor gene identified to date in this LOH region in breast tumours is CDH1 (E-cadherin)." (PMID 24069272, 2013). "A meta-analysis of primary breast tumours revealed significant associations between CCND1, ID1, CDH1 (E-cadherin) and recurrence-free survival." (PMID 21955753, 2011).
breast tumor (continued). "In our study, we correlated the hypermethylation at the CDH1 locus and the E-cadherin expression levels determined by immunohistological analysis in 79 unselected primary breast tumors." (PMID 16512896, 2006). "Together, this suggests that ZFHX1B and SNAI2 are the predominant transcriptional regulators of CDH1 accounting for the EMT phenotype of breast tumour cell lines." (PMID 16495925, 2006). "We first determined mRNA levels of NME4 (encoding NDPK-D), CDH1, and KRT18 (encoding the two well-known epithelial markers E-cadherin and cytokeratin 18, respectively), in an important cohort of 526 human breast tumors from patients with well-documented follow-up by using RT-qPCR." (PMID 34674701, 2021). "Our finding of a monotonic reduction in breast tumor CDH1 methylation with increasing age at first birth is counter to our hypothesis and could be due to chance with less than 10 methylated cases in each age stratum." (PMID 31533668, 2019). "This relationship is recapitulated in studies showing that absence of Cdh1 caused an increase in Skp2 and increased breast tumor growth in a xenograft model whereas elevation of Cdh1 had the opposite effect." (PMID 23029392, 2012). "This is also in concordance with a previous immunohistochemical study of 491 breast tumors where high expression of mesenchymal markers (i.e., vimentin, N-cadherin) and low expression of CDH1 were found almost exclusively in the triple-negative subgroup of tumors." (PMID 20813035, 2010). "In conclusion, our data indicate that CDH1 promoter hypermethylation but not CDH1 mutational inactivation is a part of an entire EMT programme resulting in breast tumour cells with a more aggressive phenotype, thus enabling metastasis formation." (PMID 16495925, 2006). "The METABRIC database (1904 human breast tumors) consistently revealed a positive association of NME4 with epithelial markers CDH1 and KRT18 and a negative association with mesenchymal markers CDH2 and VIM as well as many EMT drivers like ZEB1, ZEB2, SNAI2, TWIST1, and TWIST2." (PMID 34674701, 2021). "Of the up-regulated miRNAs in the metastatic line, miR-9 has been reported to target E-cadherin and CDH1, the E-cadherin-encoding messenger RNA; overexpression of miR-9 in non-metastatic breast tumor cells enables such cells to form pulmonary micrometastases in mice." (PMID 21980368, 2011). "Across the 112 684 cells analysed from primary breast tumours, a similar number of cancer cells expressed epithelial markers (EPCAM, CDH1 and ESR1)." (PMID 37691350, 2023). "Of the 35 upregulated genes, 5 were all related to breast tumor types: CASP8 (0.7-fold upregulation), CDH1 (1.21-fold upregulation), GATA3 (3-fold upregulation), ESR1 (3-fold upregulation) and FOXA1 (+ 2.89-fold upregulation)." (PMID 31182966, 2019). "Patients’ breast tumors were separated according to PAM50 intrinsic subtypes (basal, HER2-positive, luminal A, luminal B, or normal), and the mean centered CDH1 expression was examined." (PMID 28750639, 2017). "CDH1 and ESR1 are frequently concurrently methylated in breast tumors, a relationship also discernible in the present study." (PMID 18221536, 2008). "IH data were available for CDH1, TFAP2A, and RBP4 proteins; and only data from antibodies exhibiting differential expression among breast tumors were reported herein." (PMID 19116033, 2008). "Our findings here demonstrate that in breast tumor cells, Cdh1 suppresses Src kinase activity independent of the E3 ligase function of APC." (PMID 31420536, 2019). "To evaluate epigenetic differences in tumor-related genes relating to ER and HER2/neu status of primary tumors, we examined the promoter methylation status of the promoter region CpG islands of eight major breast tumor-related genes (RASSF1A, CCND2, GSPT1, TWIST, APC, NES1, RARβ2, and CDH1)." (PMID 18485221, 2008).
breast tumor (continued). "CDH1 and ELF3 were expressed at a significantly higher level in cells with an epithelial morphology, whereas FN1, FOSL1, VIM, ZFHX1B, SNAI2, SERPINE1 and TFGB1 showed a higher expression in fibroblastic breast tumour cells." (PMID 16495925, 2006). "Our analysis of clinical cancer tissues revealed that CDH1/E-cad expression was downregulated only in a few types or subtypes of tumors among the large group of tumor types or subtypes examined; ILC happens to be a subtype of breast tumors in which E-cad expression was downregulated." (PMID 37189027, 2023).
non-small cell lung carcinoma (134 papers, 2008 to 2026). A group of at least three distinct histological types of lung cancer, including non-small cell squamous cell carcinoma, adenocarcinoma, and large cell carcinoma. "It was previously studied that miR-25-3p is upregulated in the cigarette smoke condensate (CSC), and promotes invasion of human non-small cell lung cancer via CDH1." (PMID 34266345, 2021). "Moreover, miR-25-3p promotes invasion of human non-small cell lung cancer via CDH1." (PMID 34266345, 2021). "Moreover, the increased expression of miR-1285-5p in non-small cell lung cancer tissues suggests its role as a potential promoter of tumor development, regulating critical behaviors, such as proliferation, invasion, and migration through interactions with genes, such as Smad4 and CDH1." (PMID 37895471, 2023). "For instance, bladder cancer patients had elevated promoter methylation of RASSF1, CDH1, DAPK, and CDKN2A genes, which was distinct from hypermethylated genes MGMT, FHIT, and hMLH1 found in NSCLC (Non-Small Cell Lung Cancer) patients." (PMID 36672415, 2023).
lung adenocarcinoma (131 papers, 1992 to 2025). A carcinoma that arises from the lung and is characterized by the presence of malignant glandular epithelial cells. "In lung adenocarcinoma, H19 is responsible for tumor progression by mediating methylation-dependent repression of CDH1 promoter." (PMID 38355574, 2024). "The inferred edge from PIK3CA to CDH1 is consistent with the finding in lung adenocarcinoma that the inactivation of the PI3K pathway significantly reduced CDH1 expression." (PMID 36928529, 2023). "It was also shown that, in the lung adenocarcinoma cell lines (A549 and H1975), lncCDH5-3:3 regulates the expression of CDH1." (PMID 35159188, 2022). "To investigate the molecular mechanisms of the oncogene activity of Cdh1 in human lung adenocarcinoma, we conducted additional bioinformatics analyses." (PMID 32015681, 2020). "No methylation of CDH1 was detected in all the 60 adjacent tissues, while among the 60 lung adenocarcinoma tissues, 17 cases showed methylation of CDH1 promoter, accounting for 28.33%." (PMID 31317666, 2019). "Subsequently, we extracted DNA from each lung adenocarcinoma cell line to design PCR primers for methylation of CDH1." (PMID 31317666, 2019). "Next, we used immunohistochemistry to determine the expression of CDH1 in the lung adenocarcinoma tissues and adjacent tissues." (PMID 31317666, 2019). "Compared with the adjacent tissues, the rate of positive protein expression of CDH1 in the lung adenocarcinoma tissues was significantly lower, which was consistent with the results shown in RT‐qPCR." (PMID 31317666, 2019). "Taken together, this study demonstrates that silencing of lncRNA H19 inhibits EMT and proliferation while promoting apoptosis of lung adenocarcinoma cells by inhibiting methylation of CDH1 promoter." (PMID 31317666, 2019). "Compared with the adjacent tissues, the lung adenocarcinoma tissues exhibited a notable increase in methylation of CDH1 promoter." (PMID 31317666, 2019). "We stained the lung adenocarcinoma TMA with antibodies against an EMT marker (E-cadherin 1 (CDH1), molecules included in the signature (SMAD7, PLAUR), and immune checkpoint markers." (PMID 30783512, 2019). "A similar Nrf2 correlation with CDH1 or VIM correlated RNA changes was performed in a smaller TCGA lung adenocarcinoma 203 patient set." (PMID 31581742, 2019). "The results exhibited that compared with the adjacent tissues, the expression of lncRNA H19 was significantly elevated and the mRNA expression of CDH1 was notably decreased in the lung adenocarcinoma tissues (P < .05)." (PMID 31317666, 2019). "At first, we found that lncRNA H19 and methylation of CDH1 were highly expressed in lung adenocarcinoma tissues compared with the normal adjacent tissues, while CDH1 expression was reciprocal." (PMID 31317666, 2019). "Then, the regulatory mechanisms of lncRNA H19 were detected mainly in concert with the treatment of overexpression of lncRNA H19, siRNA against lncRNA H19, overexpression of CDH1 and demethylating agent A‐5az in lung adenocarcinoma A549 cell." (PMID 31317666, 2019). "Herein, we conducted this study to explore the effects of lncRNA H19 and CDH1 on lung adenocarcinoma with the involvement of methylation of CDH1, with the hope to raise the life quality of patients with lung adenocarcinoma." (PMID 31317666, 2019). "In order to investigate the correlation between CDH1, CDH1 methylation and lung adenocarcinoma, we initially performed RT‐qPCR to determine the expressions of cellular factors in the lung adenocarcinoma tissues and adjacent tissues." (PMID 31317666, 2019). "The effects of CDH1/lncRNA H19 on the EMT‐related factors in lung adenocarcinoma cell line A549 were explored by Western blot analysis." (PMID 31317666, 2019).